NOTCH2 (notch receptor 2)
Diseases named in the same sentence as NOTCH2 in open-access papers (continued):
Sharing a sentence is not in itself a finding about the gene and the disease.
tumor (342 papers, 2007 to 2026). "We hypothized that DLL4 is directly associated to Notch2 and/or Notch3 receptors resulting in Notch downstream activation and increased tumor cell proliferation." (PMID 39951484, 2025). "In our study, the CTNNB1, FBXW7, NOTCH2 mRNA as well as the ARID1A promoter hypermethylation biomarkers were associated with the HGSOC tumor stage, suggesting possible implications for the prognosis, despite our study lacking more in-depth prognosis data." (PMID 40002854, 2025). "C2 displayed amplifications in MYC and NOTCH2, potentially linked to aggressive tumor phenotypes, along with deletions in RB1 and CSMD1, which are associated with tumor suppressor loss." (PMID 41568381, 2025). "ssGSEA revealed that NOTCH2 expression was significantly correlated with immune cell infiltration across multiple tumor types, with particularly strong associations observed in COAD, LUSC, and PAAD." (PMID 41200204, 2025). "Particularly in the TME, NOTCH2 function is more inclined to drive the formation of M2-like tumor-associated macrophages (TAMs)." (PMID 41200204, 2025). "For instance, in colorectal cancer, NOTCH2 activation is linked to tumor-associated macrophages (TAMs) favoring M2-type polarization, known for immunosuppression and a pro-tumor microenvironment." (PMID 39184916, 2024). "Notch2 deficiency reduces the anti-tumor efficacy of dendritic cells (DCs), impacting T cell-mediated anti-tumor responses such as differentiation, migration, and antigen cross-presentation to CD8 + T cells." (PMID 38844562, 2024). "The loss of Notch1 or Notch2 in melanocytes appeared to accelerate tumor formation and growth in BP mice, and lead to shorter survival compared to control mice." (PMID 36672468, 2023). "Changes in NOTCH2 expression were significantly associated with tumour differentiation grade (p = 0.03) while HES1 expression—with tumour histological type (p = 0.007)." (PMID 35136410, 2022). "For example, tumor suppressor miR-195-5p inhibits GATA3-mediated secretion of IL-4 in CRC cells and ultimately M2-like tumor-associated macrophages polarization by suppressing the NOTCH2 expression." (PMID 35574420, 2022). "In contrast, Jag1 deletion induces the ectopic expression of Dll4 in hepatocytes along with the loss of Notch2 signaling, leading to the tumor progression." (PMID 35064244, 2022). "For example, NOTCH2 was reported to be highly expressed in HCC tumor tissues, and Yes-associated protein (a member of the Hippo signaling pathway) was found to induce the oncogenesis and excessive growth of HCC." (PMID 33686022, 2021). "Of note, an additional NOTCH2 mutation was only present in a tumor biopsy with CD30-expression of large-cell transformed lymphoma cells; this mutation was otherwise absent in all further CD30-negative samples." (PMID 34771672, 2021). "Antitumor immune responses are known to be impaired upon loss of NOTCH2 signaling as NOTCH2-deficient mice exhibited increased tumor growth rates." (PMID 33117406, 2020). "Combining the results of MutSig2CV with those of our integrative topological approach singled out new low-prevalence mutated genes, such as NOTCH2, as potential drivers of tumor progression in LGG." (PMID 32732999, 2020). "Analysis of Notch2 expression in normal mammary tissue and breast tumors, in association with clinical data, also sustained a tumor suppressor function for this receptor." (PMID 31379945, 2019). "Co-occurring alterations included a NOTCH2 copy number gain in the PDE4DIP-NOTCH2 fusion positive tumor and PDGFRB mutations in both fusion-positive cases." (PMID 31480474, 2019). "In FL, mutations in NOTCH1 and NOTCH2 are significantly associated with FL HT or the presence of DLBCL zones in the FL tumor." (PMID 30802265, 2019).
tumor (continued). "Our findings showed that the trends toward lower expression of KLF2 and higher expression of NOTCH2 were linked tumor progression." (PMID 28887496, 2017). "In a model of small cell lung cancer Sriuranpong and colleagues demonstrated that the overexpression of the active forms of Notch1 and Notch2 causes the block of cell cycle at G1 phase and the arrest of the tumor growth." (PMID 27929540, 2016). "Regarding nuclear NOTCH2 expression, positive expression (weak/moderate/strong) was associated with lower tumor stages (pT1 + pT2), compared to advanced tumor stages (pT3 + pT4) (p = 0.027; pmax = 0.043)." (PMID 25954607, 2015). "Expectedly, C8orf4-deficient tumours showed elevated expression levels of NOTCH2 target genes such as HEY1, HES6 and NRARP." (PMID 25985737, 2015). "In the subgroup of neoadjuvantly treated GC patients, we identified only a trend toward an association of a higher NOTCH1 and NOTCH2 expression in the pretherapeutic biopsies and worse tumor regression after chemotherapy." (PMID 25954607, 2015). "The mutation frequency of NOTCH2 gene in PNM was significantly higher than that in the tumor." (PMID 35515115, 2022). "On the other hand, Notch2 expression was associated with the progression of pancreatic intraepithelial neoplasia (PanIN) in a mouse model by altering the cytokine networks and tumour microenvironments." (PMID 35954379, 2022). "Besides, loss of Nf2, a Hippo pathway tumor suppressor, results in increased expression of Notch2 in cholangiocytes." (PMID 35508987, 2022). "The results showed that NOTCH2 overexpression could recover the decreased tumor volume and weight caused by MIR99AHG inhibition." (PMID 34911544, 2021). "Overactive Notch2 signaling has been linked to the dysregulation of certain miRNAs, tumor-associated stromal cell input, and the modulation of internal and external stimulation conditions in tumor cells that contribute to chemo- and radio-resistance." (PMID 34440225, 2021). "Interestingly, co-occurring alterations included a NOTCH2 copy number gain in the PDE4DIP-NOTCH2 fusion tumor and PDGFRB mutations in both fusion-positive cases." (PMID 31480474, 2019). "Deregulation of NOTCH2 signaling is implicated in a wide variety of human neoplasias." (PMID 28736522, 2017). "Finally, in order to further evaluate a potential tumor suppressor genetic model we searched for point mutations of the NOTCH2 gene in four of our OD cases." (PMID 19119320, 2009). "To test this hypothesis, we screened for somatic mutations the complete coding sequence of NOTCH2 gene in four tumor and paired peripheral blood derived DNAs." (PMID 19119320, 2009). "We found that NOTCH2 is a common deletion target in OD as well as in GBM, raising the hypothesis of a possible causal relationship between NOTCH2 status and tumor behavior." (PMID 17593975, 2007). "Moreover, a widespread multi-omics analysis in more than 32 cancer types from The Cancer Genome Atlas (TCGA) dataset identified a genomic signature of 11 genes, correlated with TMB, able to predict the response to immunotherapy, which included FAT1 and NOTCH2, both mutated in our patient’s tumor." (PMID 40248199, 2025). "Furthermore, Notch2 function seems to be essential for the proper development of the immune system under normal conditions, and gain-of-function mutations play a critical role in tumor immunity." (PMID 34205690, 2021).
tumor (continued). "However, this proof of concept serves as a perspective and may justify further explorations of the therapeutic potential of gliotoxin in NOTCH2 associated human neoplasias." (PMID 28736522, 2017). "However, our results were in contrast to findings from other studies mainly performed in Asian countries, which have reported a contribution of higher expression of NOTCH1 or NOTCH2 to tumor progression and, in particular, an association of higher expression of NOTCH1 with worse prognosis." (PMID 25954607, 2015). "Notch receptors exert context- and subtype-specific roles: Notch1 and 4 promote tumour aggressiveness, whereas Notch2 often exhibits tumour-suppressive roles." (PMID 41894035, 2026). "Addition of exogeneous DLL4 resulted in enhanced tumor cell numbers via Notch2 and/or Notch3-mediated canonical pathway activation." (PMID 39951484, 2025). "Taken together, these findings suggested that during the PanIN stage, NOTCH2 primarily exerted tumor-suppressive functions by maintaining differentiation and suppressing aberrant proliferation." (PMID 41200204, 2025). "Among the ligands, DLL1 regulates cell-cell communication, DLL3 inhibits apoptosis induction, DLL4 activates the NF-κB pathway, promoting VEGF expression; JAG-1 promotes angiogenesis, and JAG-2, upon binding Notch-2, activates tumor cell proliferation." (PMID 41200177, 2025). "We found that protein expression was upregulated in 43.57%, 45%, 56.31%, and 42.71% of tumor tissue in Notch1, Notch2, Notch3, and Notch4, respectively." (PMID 41027955, 2025). "Following failure of standard first line chemotherapy, high-throughput sequencing (HTS) revealed a high tumor mutational burden (TMB), pathogenic mutations in FAT1 and NOTCH2 and a microsatellite instability (MSI)-associated signature." (PMID 40248199, 2025). "In contrast, increased plasma cell infiltration was observed in the low-NOTCH2 group, suggesting a potential role in anti-tumor immunity." (PMID 41200204, 2025). "The high-NOTCH2 expression group showed significant enrichment in multiple tumor-promoting pathways, including PI3K-AKT, TGF-β, MAPK, mTOR, and KEAP1-NFE2L2 signaling." (PMID 41200204, 2025). "The “Generated Blacklist” impacted 15 cancer drivers, including the NOTCH2 oncogene and tumor suppressor, with very strong confidence." (PMID 39975128, 2025). "The different therapy response was related to the CD8:Foxp3 lymphocyte ratio, higher in complete response to therapy, thus interestingly correlating NOTCH2 to the composition of the tumour microenvironment." (PMID 41008920, 2025). "NOTCH1 has been revealed as a tumour suppressor; in contrast, NOTCH2 and NOTCH3 have demonstrated an oncogenic role in BCa." (PMID 41008920, 2025). "Pan-cancer analysis of the TCGA dataset revealed elevated NOTCH2 expression in several tumor types, including CHOL, GBM, KIRP, and STAD, whereas its expression was markedly reduced in BLCA, KICH, and PAAD." (PMID 41200204, 2025). "The Notch pathway plays an important role in SCLC tumor heterogeneity, and Notch2, an MDK receptor candidate, is an airway neuroendocrine stem cell marker." (PMID 40620228, 2025). "Among all the Notch expression profiles, only NOTCH2 had a statistically significantly higher expression/upregulation in PDS than AFX tumor cells (OR: 1.02, 95% CI: 1–1.03, p = 0.01)." (PMID 40387567, 2025). "For instance, overexpression of the intracellular domain of Notch2 has been reported to suppress tumor growth, and elevated levels of Notch2 correlate with better patient survival outcomes." (PMID 41463075, 2025). "In their orthotopic xenografts, stable silencing of NOTCH2 significantly inhibited tumour growth, reducing NOTCH2 and HEY1 expression and decreasing EMT and stem cell markers." (PMID 41008920, 2025). "After Notch2 silence, the livers were significantly smaller, the tumor number and area, and liver weight ratio were also significantly reduced following SBT treatment, compared with the control group." (PMID 39972058, 2025).
tumor (continued). "Mechanistically, it has been shown that NUSAP1 can stabilize NOTCH2 by inhibiting its ubiquitination, thereby activating NOTCH2 signaling and promoting tumor progression and chemoresistance." (PMID 41200204, 2025). "Enhances radiotherapy efficacy by sponging miR-296 to elevate NOTCH2, thereby promoting NK cell-mediated tumor clearance." (PMID 41409273, 2025). "The dysregulated pathway as a result of the BRCA2 mutation resulted in genomic instability, which allowed tumor progression and proliferation via the NOTCH pathway, as seen in the patient with a BRCA2 mutation alongside an aberrant NOTCH2." (PMID 39199639, 2024). "Organoid lines also exhibited somatic mutations in RCC‐related genes which were in concordant with respective tumor including ESPL1, SMARCB1, RAB21, NCOR1, NLRC5, NOTCH2, and FOXA2 mutations." (PMID 38923304, 2024). "Knockout of TBC1D15, Notch1, or Notch2 alone or in combination was observed to reduce the tumor masses in these animals." (PMID 38409448, 2024). "Notch 2 was also identified at the level of hepatocellular carcinoma metastases, while Notch 4 promoted tumor aggressiveness and metastasis." (PMID 38927059, 2024). "The possible driver genes in the tumor sample were screened as ARID1B, MAX, NOTCH2 and APC, in which a missense mutation of base C instead of base T occurred in the NOTCH2 gene located at position 120,471,691 on chromosome 1." (PMID 38730456, 2024). "Studies have shown that an increase in Notch1 and Notch3 is associated with lower DFS in triple-negative and HER-2+ tumors while blockade of Notch 2 and 3 can reduce tumor growth and the frequency of tumor cell initiation." (PMID 39735530, 2024). "By adding MT- or MTGCSF−/−-CM to the cultures, we found that tumor-derived GCSF was equally potent at blocking cDC1s propagated with DLL1/NOTCH2 signaling." (PMID 36911097, 2023). "The γ-secretase inhibitor DAPT blocks Notch2 and has the same tumorigenic effects of promoting tumor cell migration, invasion, and proliferation." (PMID 37728427, 2023). "Conclusively, this paper identifies a high NOTCH2 P2113S mutation rate in OC using WES, with these mutations associated with tumorigenesis by enhancing the ability of tumor cells to migrate, invade, and proliferate." (PMID 37728427, 2023). "Consistently, tumor xenograft models uncovered that knockdown of Notch2 obviously inhibited LINC01977-induced tumor growth." (PMID 37198207, 2023). "N-cadherin homotypic interactions between CLL cells and bone marrow-derived MSCs allow tumor cells to induce Notch2 activation in stromal cells." (PMID 37255594, 2023). "FBXW7, a well-known tumor suppressor, has been demonstrated to control the degradation of some oncoproteins such as cyclin E, c-Myc, Yap and Notch2." (PMID 35094292, 2022). "The continuous Notch2 signal promotes tumor cell EMT while avoiding apoptosis, and the increase of Notch2 expression is related to the poor clinical prognosis of patients." (PMID 35600868, 2022).
tumor (continued). "AEA inhibits tumor growth of cholangiocarcinoma cells via upregulation and activation of Notch1, whereas 2-AG promotes tumor growth through upregulation and activation of Notch2." (PMID 36291926, 2022). "Targeting MYC and NOTCH2 also decreased the capacity for self-renewal and tumor formation corroborating the importance of the MUC1-C→MYC→NOTCH2 pathway in driving the SCLC CSC state." (PMID 35612556, 2022). "As expected, the growth rate of tumors from LINC01806-silenced NSCLC cells slowed down compared to that in sh-NC group, whereas the reduction in tumor growth rate was restored when NSCLC cells were co-transfected with antagomir-4428 or pcDNA3.1/NOTCH2." (PMID 35599309, 2022). "To date, the meaning and regulation of Notch2 was demonstrated in fetal mouse testes and in tumor Leydig cells." (PMID 34679887, 2021). "Numerous articles have examined the promoting or limiting impact of Notch1 and Notch2 on cell lines, tumor xenografts, animal models, and human tumor specimens." (PMID 36643842, 2021). "Numerous previous studies have identified genes associated with HCC oncogenesis, including NOTCH2 and β-CATENIN; however, most of these studies have focused on differentially expressed genes (DEGs) between normal and tumor tissues." (PMID 33686022, 2021). "Integrated WGS and tNGS analysis clearly distinguished this tumor type from EBV-negative DLBCL due to frequent mutations in ARID1A (45%), KMT2A/KMT2D (32/30%), ANKRD11 (32%), or NOTCH2 (32%)." (PMID 34039950, 2021). "Tumor cells exhibit Notch signaling over-expression, high Notch-1, and Notch-2 levels, while a poor expression of Notch signaling related factors is exhibited by the normal pancreas." (PMID 33670230, 2021). "The main conclusion from this study is that Notch2 activation in the microenvironment is required for the activation of canonical Wnt signaling in tumor cells, through the inhibition of GSK3-β and the stabilization of β-catenin." (PMID 34298607, 2021). "A monoclonal antibody OMP-59R5 that selectively targeting Notch2 and Notch3 can inhibit xenograft tumor growth." (PMID 34988077, 2021). "Increased Notch homolog 2 (Notch2 expression in LUAD patients can induce a high tumour recurrence rate, and high expression of Notch1 and Notch3 is related to adverse prognosis in LUAD." (PMID 34112123, 2021). "Next-generation sequencing demonstrated mutations in FLT3, NOTCH2, and KMT2A, microsatellite stability, and a tumor mutational burden of 2 mut/Mb." (PMID 34292677, 2021). "Four Notch receptors have been associated with tumor growth (Notch1, Notch2, and Notch3), CSC regulation (Notch1, Notch2, Notch4), tumor invasion and metastasis (Notch1, Notch2, Notch3, Notch4), angiogenesis (Notch3), and drug resistance (Notch1 and Notch3)." (PMID 34207383, 2021). "Notch2 is highly expressed in hepatocellular carcinoma and non-small-cell lung cancer, promotes proliferation of stem-like tumor cells and increases cell resistance to radiotherapy." (PMID 34224316, 2021). "We observed significant increases in Sox2 and Notch2 expression in tumor cells isolated from obese mice compared to those from lean mice." (PMID 32098183, 2020). "Stable knockdown of Notch 2 in TNBC xenografts demonstrated enhanced tumour growth, and notably Notch 1 was overexpressed in these tumours, suggesting an underlying mechanism of compensation." (PMID 32575680, 2020). "EZH2, HMGB3 and UCK2 expressed higher in tumor compared with normal tissues, while NOTCH2 and ODF2 expressed lower in tumor compared with normal tissues." (PMID 32699528, 2020). "We assessed the expression of NOTCH2 in mouse tumor xenografts by immunohistochemical staining and found that NOTCH2 expression in the si-circKIF4A group was significantly decreased." (PMID 32457613, 2020).